TNF (tumor necrosis factor)
Diseases named in the same sentence as TNF in open-access papers (continued):
Sharing a sentence is not in itself a finding about the gene and the disease.
tumor (continued). "Reinforcing this idea, recent preliminary data obtained in our laboratory with the L929 tumor cell lineage, which is sensitive to TNF-α, showed that astrocytes release TNF-α when stimulated by glutamate (data not shown)." (PMID 23984387, 2013). "Tumor promotion by TNF-α can involve diverse pathways, including enhancement of tumor growth and invasion, leukocyte recruitment, angiogenesis and facilitation of mesenchymal transition." (PMID 24325392, 2013). "High expression of IL-6 and TNFα exhibited a close correlation with high expression of VEGF in the tumor cells (r = 0.714, p < 0.0001 and r =0.702, p < 0.0001 respectively)." (PMID 23688241, 2013). "TNFα was added to each of the single cell cultures at a concentration of 1 ng/ml, which is similar to the concentration found in the tumor microenvironment." (PMID 23874303, 2013). "TNF-α has direct effects on a variety of cell types and has been shown to work together with NO in tumor cell cytotoxicity." (PMID 23964349, 2013). "In cancer cells, TNF signalling is a mixed blessing as TNFR1 can trigger apoptotic cell death of tumour cells, but under most circumstances the signalling originating from TNFR1 is pro-inflammatory." (PMID 23852022, 2013). "The armed ATC are the presumed source of the Th1 cytokines and their secretion would serve to activate microglia (IFN-γ), act as an adjuvant for immunization of endogenous lymphocytes (GM-CSF) and potentially augment the killing of target tumor cells (TNF-α)." (PMID 23433400, 2013). "A mutation in VHL gene results in increased production of cytokines including TNF, which sensitizes local tumor cells to TNF actions." (PMID 24350291, 2013). "TNF was shown to enhance tumor cell metastasis in several in vivo mouse models including an orthotopic xenotransplantation model of PDA with pancreatectomy-induced metastasis." (PMID 24098720, 2013). "CAR-expressing T cells produced abundant quantities of IL-2, INF-γ, and TNF-α, demonstrating activation of both cytolytic and cytokine effector mechanisms after tumor recognition." (PMID 24358223, 2013). "These T cells effectively lysed a variety of CD20+ tumor cells at low E:T ratios and secreted abundant IFNγ, TNF-α, and IL-2 upon tumor recognition, highlighting their CD20 specificity and potent effector function." (PMID 24358223, 2013). "Moreover, the clinical chemotherapeutic agent, paclitaxel, has been shown to induce soluble TNF-α production in macrophages, and these alterations in tumor necrosis factor signaling pathways are associated with cytotoxicity and resistance to taxanes in tumor cells." (PMID 23573150, 2013). "TNF, IFNγ, IL-6 and IL-11 gene expression were higher in non-tumor tissue from Iron/DSS and Control/DSS mice compared with colonic tissue from Iron and Control mice at day 78 (data not shown)." (PMID 24223168, 2013). "Nevertheless, despite their apparent sensitivity to TNFα-induced cytotoxicity, tumor cells that were exposed to the combined stimulation were endowed with higher resistance to doxorubicin." (PMID 24369447, 2013). "The tumor cells used in this study (MCF-7 cells) are known to be sensitive to TNFα-induced cytotoxicity; accordingly, approximately 40% of the tumor cells were killed in vitro by their exposure to the combined stimulation of TNFα + Estrogen + EGF." (PMID 24369447, 2013). "TNF-α is a pro-inflammatory cytokine that creates tumor microenvironment fostering tumor development by induction of tumor promoting cytokines, release of matrix metalloproteinases (MMPs) and pro-angiogenic activity." (PMID 23457494, 2013). "Tumor cells released NF-κB-dependent MMPs by NF-κB-mediated TNFα production of immune cells in tumor microenvironment." (PMID 23997800, 2013). "TNF-α is known for as the strongest antitumor cytokine in the current time, plays a key role in killing tumor cells and in hemorrhagic necrosis as well as in immunity." (PMID 23593411, 2013).
tumor (continued). "Tumor necrosis factor-alpha (TNF-α) was reported as anticancer therapy due to its cytotoxic effect against an array of tumor cells." (PMID 23573150, 2013). "The liberation of multiple proinflammatory cytokines, including IL-1, IL-6, and TNF-α from the tumor microenvironment results in the induction of CRP synthesis from the liver." (PMID 24130817, 2013). "TNF-α is a potent inducer of viral gene expression in certain tumor cell lines harboring integrated, latent HIV-1, through the activation of NFκB." (PMID 24385908, 2013). "The cytokine TNF-α promotes tumor proliferation by inducing the release of matrix metalloproteinase (MMP), particularly the gelatinases MMP-2 and MMP-9, which promote tumor growth and metastasis." (PMID 23977085, 2013). "Removal of scrib−/− or lgl−/− cells from the epithelium also requires TNF/Eiger indicating a conserved role for TNF signaling as a tumor suppressor pathway in Drosophila within these genetic contexts." (PMID 24392358, 2013). "Phosphatase inhibition and the tumor necrosis factor-α (TNF-α) induction have been shown to play an important role in the biochemical process of tumor promotion in several organs, including skin, liver and stomach." (PMID 24217398, 2013). "After treatment, tumour volume and mass, plasma biochemistry, oxidative stress in liver and tumour, TNF-α level in liver and tumour homogenates, and survival rates were analysed." (PMID 23408945, 2013). "In the model of p-glyco-protein 2 (Mdr2)-knockout mice, TNF-α and the activation of NF-кB accelerated the process of tumor in the occurrence of HCC." (PMID 24066693, 2013). "During recall assays in animals immunized with βhCG-TT + MIP, TT also induced significantly heightened levels of IFNγ and TNFα, cytokines with significant anti-tumor activity." (PMID 23593454, 2013). "Apart from contact dependent cytotoxicity, CTL control tumour growth by secretion of TNF-α and IFN-γ." (PMID 23922331, 2013). "Additional analyses indicated that the morphological changes induced by TNFα + Estrogen + EGF in the tumor cells were accompanied by redistribution of focal adhesion kinase (FAK) and paxillin, two key regulators of cell adhesion and spreading." (PMID 24369447, 2013). "mRNA expression of CD44 was also measured for all conditions (IL-6, TNF-α, tumor spheroid, and plasma) via real time quantitative PCR (qPCR)." (PMID 23372803, 2013). "It seems that the tumor suppression effect with Ssd in combination of TNF-α is probably contributed by downregulation of NF-κB signaling." (PMID 23573150, 2013). "Further co-culture experiments between astrocytes and several lung cancer derived cell lines indicate that astrocytes secrete IL-6, TNF, and IL-1β, which stimulate tumor cell growth." (PMID 23596394, 2013). "TNF-α has been recently shown to promote tumor development in experimental carcinogenesis, and TGF-β has been shown to attenuate an anti-tumor immune-response through the induction of regulatory T cells in spontaneous and inflammation associated cancer." (PMID 24015203, 2013). "Since TNF-α enhances the toxic effects on tumor cells of 17-DMAG, it was determined that the effects of the drugs on apoptosis in all of these 4 types of cells." (PMID 23635099, 2013). "Tumor necrosis factor (TNF)-α is one of the most potent pro-inflammatory cytokines produced in the tumor microenvironment." (PMID 23437179, 2013). "Both LM5G8 and B16-F10 tumor cells produced undetectable levels of mouse TNF-α in the culture supernatant (< 25 pg/ml) as assessed by ELISA (data not shown)." (PMID 24376728, 2013). "We demonstrate here a pro-tumorigenic function of systemically active TNF as the treatment of tumor-bearing mice with this cytokine significantly increased tumor growth." (PMID 24098720, 2013). "We additionally measured TNF-α expression, since it has direct anti-tumour function, and also plays a major role in leukocyte recruitment to the brain." (PMID 23717511, 2013).
tumor (continued). "In contrast, TNF-α also promotes tumor activity by stimulating the proliferation of cervical cells immortalized and transformed by HPV." (PMID 23870134, 2013). "With regard to different groups, respectively 10 mice of Hep-2/TIC group, 11 mice of Hep-2/CD group, 11 mice of Hep-2/TNF-α group and 12 mice of Hep-2/0 group developed tumor." (PMID 23593411, 2013). "Upon ligation of activating receptors, NK cells can also release cytotoxic molecules as FasL and/or TNFα which kill tumor target cells." (PMID 23667543, 2013). "Taken together, these findings suggest that the therapeutic mechanism of antitumor immune mediated by RdB/IL23/p35 is associated with the generation and recruitment of IFN-γ- and TNF-α-co-expressing T cells in tumor microenvironment." (PMID 23844018, 2013). "Tumor necrosis factor related apoptosis inducing ligand (TRAIL) as a member of the TNF gene superfamily induces apoptosis primarily in tumor cells." (PMID 24349222, 2013). "In contrast, a fraction of wild type (37.5%), TNF deficient (12.5%), and TNFR2 deficient mice (22.2%) were able to fully reject the tumor within two weeks." (PMID 24098720, 2013). "Tumor necrosis factor (TNF), have been shown to mediate tumor initiation, promotion, and progression." (PMID 24363771, 2013). "Mounting evidences suggested that TNFα mediates many critical processes of tumor progression, including oncogene activation, DNA damage, and tumor metastasis." (PMID 23431386, 2013). "To show that this microRNA regulates the expression of EMMPRIN, we next neutralized its activity by transfecting the tumor cells with its antagomir anti-miR-146a and then co-culturing them with the U937 monocytes in the presence of TNFα." (PMID 23874303, 2013). "This supports our model that increased NF-κB activity in keratinocytes leads to a TNF-independent tumor formation which remains limited to the basal membrane." (PMID 23977171, 2013). "Because TNFα expression is abundant in tumor microenvironment, and its expression is correlated with poor prognoses, we investigate effects of Saussurea lappa Clarke (SLC) on highly metastatic MDA-MB-231 cells." (PMID 23997800, 2013). "Depending on the amount of TNF that reaches the tumor mass, its effects range from EC activation, to increased vessel permeability, EC damage, and massive hemorrhagic necrosis." (PMID 24062984, 2013). "Conversely, in vitro, IL-1β has been implicated in inducing glioma invasion, as well as promoting tumor growth via autocrine induction of TNF signaling." (PMID 23596394, 2013). "TNF-α, Th1 cytokine, has a significant role in promoting tumor-specific immune response via enhancement of CTL development and cytotoxicity as well as antigen presentation." (PMID 23844018, 2013). "The family of TNF inhibits tumor formation through apoptosis but TNFs deregulation encourages metastasis, migration and invasion of tumor cell tissues." (PMID 23724937, 2013). "TNF-α was reported as anticancer therapy due to its cytotoxic effect against a number of tumor cells." (PMID 23573150, 2013). "Based on these studies, we propose that TNFα is the factor that dominated the high protumoral phenotypes and responses, leading to its most extreme impact on tumor cell spreading to remote organs." (PMID 24369447, 2013). "Leukocyte infiltration includes B- and T-lymphocytes and TAM also produce TNF which modulate, tumor growth." (PMID 24350291, 2013). "Dysregulated TNF expression within the tumor microenvironment appears to favor malignant cell tissue invasion, migration, and ultimately metastasis." (PMID 23936772, 2013). "When conjugated to a vascular homing peptide and targeted to tumors, TNFα resulted in a switch from M2 to M1 macrophages, which was accompanied by normalization of tumor vasculature and enhanced infiltration of CD8 T cells." (PMID 24265631, 2013).
tumor (continued). "A similar compound, consisting of TNF fused to another tumor-vasculature-homing peptide (RGR) has been recently shown to stabilize tumor vessels and to enhance active immunotherapy in experimental pancreatic neuroendocrine tumors." (PMID 24062984, 2013). "Tumor necrosis factor α (TNFα), a proinflammatory cytokine predominantly produced by macrophages, is a key molecule regulating the inflammatory processes in tumor promotion." (PMID 23431386, 2013). "We have recently shown a similar mechanism in the B16F10 pulmonary metastasis model where exogenous TNF treatment enhanced tumor growth in a Treg-dependent manner." (PMID 24098720, 2013). "TNF has a powerful anti-tumoral activity but if cytokines remain in body for a long time, they lose their anti tumor activity." (PMID 24171078, 2013). "As shown herein, while SEG induced robust production of nitrite from PBMCs and robust tumor cell cytotoxicity, it also displayed substantially lower quantities of TNF-α and IFN-γ relative to other egcSEs." (PMID 23964349, 2013). "TNF-α is highly expressed by many human tumor types and plays a critical role in the induction of the pro-angiogenic phenotype of macrophages." (PMID 24314323, 2013). "DEN-induced tumors share similar pathogenesis, in which pro-inflammatory cytokines such as IL-6 and TNFα promote tumor development." (PMID 24339898, 2013). "NO is known to sensitize tumor cells to TNF-α-mediated apoptosis via specific disruption of the TNF-α-induced generation of hydrogen peroxide and subsequent inhibition of the NF-κ B dependent expression of anti-apoptotic genes." (PMID 23964349, 2013). "The IFN-γ- and TNF-α-co-secreting T cell population was dramatically greater in tumor tissues treated with RdB/IL23/p35 than those in tumors treated with either RdB/IL12 or RdB/IL23 alone." (PMID 23844018, 2013). "Here, it is interesting to note that the single cells that migrated out of tumor-spheroids formed in the presence of TNFα + Estrogen + EGF stimulation expressed lower levels of E-cadherin compared to the cells that remained in the spheroids." (PMID 24369447, 2013). "Thalidomide is a tumor necrosis factor alpha (TNFα) inhibitor which has been found to have abilities against tumor growth, angiogenesis and inflammation." (PMID 23405115, 2013). "We also found that activated adipocytes trigger tumor cell proliferation by increasing either TNF-α or VEGF levels." (PMID 24015203, 2013). "Transmissibility of neoplasia was preventable by prior neutralization of inflammation using anti-TNF-α antibody in infected MLN donor mice." (PMID 23991210, 2013). "In DT-treated mice, significantly more CD4+CD154+ T cells expressed the cytokines IFN-γ, TNF-α, and IL-2 than in mice receiving only tumor cells." (PMID 22890822, 2013). "TNF-α, another Th1 cytokine produced by activated T cells, induces tumor cell necrosis and enhances the activity of NK and T cells." (PMID 24382970, 2013). "Xenograft 1016 (X1016) tumor was briefly cultured as neurospheres in vitro and stimulated with TNF-α for various times." (PMID 24244348, 2013). "Alternatively, a prodrug scFv:FasL-based strategy analogous to that reported for scFv:TNF has been pursued to ensure tumor-restricted FasL-induced signaling." (PMID 23840967, 2013). "We have found that tumor-infiltrating γδT17 cells induced by tumor-elicited inflammation can promote tumor progression via secretion of IL-17, IL-8, TNF-α, and GM-CSF to form an immunosuppressive microenvironment in human CRC (unpublished data)." (PMID 24382972, 2013). "Recently, it was found that culturing human bone marrow mesenchymal stem cells (HBMSCs) with tumour necrosis factor-α (TNF-α) enhanced their tumour-suppressive properties through the upregulation of multiple genes with cancer apoptotic activity." (PMID 23815673, 2013).
tumor (continued). "It was seen that tumor was growing fast in the nude mice of control (Hep-2/0) group; tumor growth in Hep-2/TNF-α group was hardly inhibited; tumor growth in Hep-2/CD group and Hep-2/TIC group was retarded, more prominently in Hep-2/TIC group." (PMID 23593411, 2013). "For promiscuously active ligands such as TNF the incorporation into advanced prodrug strategies can further help to ensure strictly tumor-localized unmasking of apoptotic activity." (PMID 23840967, 2013). "In our study, both in vivo and in vitro experiments confirmed the synergic anti-tumor effect of CD gene and TNF-α gene when using in combination." (PMID 23593411, 2013). "The question of the effect of anti-TNF-alpha in skin carcinogenesis is especially relevant in view of the increased use of these drugs for the treatment of autoinflammatory immune diseases." (PMID 23533798, 2013). "TNF-α is an important immune mediator in inflammatory response and has been suggested to be an endogenous tumor promoter in human carcinogenesis." (PMID 23326309, 2013). "When used singly, TNFα was more effective than the other two representatives of the tumor microenvironment—estrogen and EGF—and its activities were potently increased by cooperating with these two factors." (PMID 24369447, 2013). "Eliminating leukocyte-derived TNF-α results in diffused vascular hemorrhage, stromal necrosis, and reduced tumor growth in MMTV-NeuT mice." (PMID 24314323, 2013). "As an example, TNF has been fused with the single chain Fv Ab L19, which is specific for the extradomain B of fibronectin expressed by the tumor neovasculature." (PMID 24062984, 2013). "Recently we reported that TNF-α can be expressed by human tumor cells as both a membrane tethered (mTNF-α) and a soluble (sTNF-α) form." (PMID 24180579, 2013). "These cells mediate these functions by secreting inflammatory cytokines, like IFN-γ and TNF-α, to induce cytotoxicity in infected cells and tumor cells." (PMID 23626860, 2013). "With the exception of TNF-α, all the cytokines investigated were also unable to induce apoptosis of the tumor cells (all P<0.05)." (PMID 23761816, 2013). "VEGF and MMP-9 are essential for tumor angiogenesis, and can be induced by a myriad of mediators found in tumor microenvironment, including hypoxia, TNFα or EMMPRIN." (PMID 23874303, 2013). "We further replicated these findings in a second model of human-derived brain metastasis and again found that systemically administered TNF increased permeability focally at tumor sites." (PMID 24108809, 2013). "The combination of IL-6 and its inducers TNF-α and IL-1β promotes tumor growth and survival in cancer patients through maintenance of chronic inflammation and induction of a tumor-supporting microenvironment." (PMID 23616009, 2013). "These anti-tumor “N1” neutrophils synthesize higher levels of TNF-α, MIP-1α, H2N2, and NO2 and show cytotoxic activity against tumor cells both in vivo and in vitro." (PMID 23577028, 2013). "Tumor necrosis induction and mediation of the immune response to bacterial, viral, and parasitic invasions are beneficial functions of TNF-α." (PMID 23533448, 2013). "The binding of TNF-α to the TNFR-2 on the surface of immune cells can induce a series of anti-tumor immune responses." (PMID 23593411, 2013). "The apoptotic effect of the egcSE CSFs appears to be mediated in part by NO and TNF-α since NO synthase inhibitor L-NMMA and anti-TNF-α antibodies significantly inhibited the tumor cell cytotoxicity." (PMID 23964349, 2013). "In 1990, Rosenberg used TNF-α gene transfected (as mediated by retrovirus) tumor infiltrating lymphocyte (TIL) to treat patients with advanced malignant melanoma and revealed remission to varied extents in these patients." (PMID 23593411, 2013). "On the other hand, TNF stimulates proliferation, survival, migration, and angiogenesis in most cancer cells that are resistant to TNF-induced cytotoxicity, resulting in tumor promotion." (PMID 23819063, 2013).